BRCA1 (BRCA1 DNA repair associated)
Diseases named in the same sentence as BRCA1 in open-access papers (continued):
Sharing a sentence is not in itself a finding about the gene and the disease.
cancer (continued). "The mutation eliminates the activity of BRCA1 in the repair of DNA damage and maintenance of genomic stability and is associated with an increased risk of cancer." (PMID 24831086, 2014). "In our cohort, the missense variants in BRCA1 are spread throughout much of the protein, whereas the cancer-associated mutations tend to cluster in the N-terminal RING domain and the C-terminal BRCT domain." (PMID 24728327, 2014). "Considering all data available for the p.Ser36Tyr BRCA1 variant (in silico predictions, clinical data, and functional assay results), it should be classified as a moderate cancer risk mutation." (PMID 24695549, 2014). "Of these, 29% presented a familial cancer history and specifically, 37.5% were carriers of germ line mutation in the BRCA1/2 genes, which was displayed by only 8.6% of the tumors from non-familial BC cases." (PMID 25006670, 2014). "Breast cancer growth rates vary considerably among cancer patients; they grow significantly faster in younger women, in recurrent cancers and in patients with BRCA1 and BRCA2 mutations." (PMID 25379013, 2014). "While mutations leading to truncated forms of BRCA1 are clearly linked to cancer phenotypes in humans, there is also an underlying selective pressure in favor of amino acid-altering substitutions in this gene." (PMID 25011685, 2014). "We focused on the specific effects caused by loss of BRCA1/2 function, which confers (epi)genetic instability in cancer cells." (PMID 25158060, 2014). "Altogether, these observations reinforced the need for screens for additional drugs that efficiently kill BRCA1/2-associated cancer cells when combined with PARPi." (PMID 24962108, 2014). "Inhibition of poly(ADP-ribose) polymerase (PARP) is a promising therapeutic strategy for BRCA1 deficient cancers, however, the development of drug resistance limits clinical efficacy." (PMID 24831086, 2014). "While the findings of increased cancer risk are in agreement with prior reports, this is the first study evaluating biologic function and clinical associations of the BRCA1-3’UTR-variant with the patients that are carriers and develop cancer." (PMID 24915755, 2014). "This genomic instability provided by such mechanisms probably underlies the cancer predisposition caused by loss-of-function mutations in BRCA1 or BRCA2." (PMID 25594033, 2014). "Wild type BRCA1 also attenuated the loss of glutathione (GSH) in response to H2O2 in human cancer cell lines, DU-145, LNCaP and MCF7." (PMID 24704793, 2014). "Cancers occur when heterozygous individuals experience a somatic loss of heterozygosity event at the BRCA1 or BRCA2 locus, leaving only the abnormal allele intact." (PMID 25011685, 2014). "PGD has been used to identify cancer predispositions in 22 common inherited cancer syndromes including breast cancer (BRCA1 and BRCA2), Gorlin syndrome, tuberous sclerosis, familial colorectal cancer, and retinoblastoma." (PMID 26237394, 2014). "Recently, significant work in the area of synthetic lethality has led to new approaches for the treatment of BRCA1/2-deficient cancers using high efficacy poly(ADP-ribose) polymerase 1 (PARP1) inhibitors (PARPi) with high efficiency." (PMID 24962108, 2014). "Thanks to a large international collaborative effort, we have been able to identify at least two SNPs that are associated with increased cancer risk in BRCA1 and BRCA2 mutation carriers respectively." (PMID 24698998, 2014). "A RING mutation (C61G), found in human cancer, destabilizes the BRCA1/BARD1 heterodimer and abrogates ubiquitin ligase activity." (PMID 24704793, 2014). "TNBC is strongly related to germ-line mutations in the BRCA1 gene, and 90% of BRCA1-mutated cancers are TNBC." (PMID 24731479, 2014). "Cancer cells deficient in BRCA1/2 are unable to maintain genomic integrity in the presence of a large number of DSBs, resulting in cell death via a synthetic lethal effect." (PMID 25158060, 2014).
cancer (continued). "While all cells of males and females with germline BRCA1 mutations exhibit a heterozygous BRCA1mut/+ genotype, cancer develops primarily in females, often at young ages and almost exclusively affects the breast and ovaries." (PMID 25400221, 2014). "The structural integrity of BRCA1 tBRCT is required for transcriptional activation activity and variants that disrupt its integrity are strongly correlated to cancer risk." (PMID 24845084, 2014). "Our results also indicate that piperlongumine can be used against PARP-inhibitor- resistant, BRCA1-deficient cancers." (PMID 25221646, 2014). "It is already known that BRCA1 exon 11 splicing isoforms are implicated in cancer, and maintaining the correct isoform proportions is important in preventing cell transformation." (PMID 25056543, 2014). "MK-4827 was found to be well tolerated in vivo and demonstrated efficacy as a single agent in a xenograft model of BRCA1-deficient cancer." (PMID 24795863, 2014). "Young women who have been identified as carrying a deleterious mutation in BRCA1 or BRCA2 face a unique set of challenges related to managing cancer risk during a demographically-dense stage of life." (PMID 24586286, 2014). "Cancer-associated mutations in the BRCT domain abrogate BRCA1 interaction with these various proteins and impair its transactivation activity." (PMID 25460500, 2014). "BRCA1 mutation-associated cancers are more sensitive to DNA damaging agents as compared to conventional chemotherapy agents." (PMID 25177489, 2014). "Actually, the PTEN and BRCA1 genes are recognized as one of the most frequently deleted and/or mutated in many human cancers." (PMID 25426449, 2014). "Cancer cells with dysfunctional BRCA1/2 acquire increased mutation rates and become sensitive to platinum drugs and PARPis due to a deficiency in error-free repair mechanisms." (PMID 25158060, 2014). "Similar results were observed using methylation-specific PCR, and BRCA1-mutated cancer specimens were classified into unmethylated and methylated groups for comparison of the protein expression of DNMT1." (PMID 24502362, 2014). "There was a calendar year of birth effect, increasing the risk of cancer for both BRCA1/2 carrier cohorts (RH ranging from 1.06 to 1.08, p > 0.0005 across all strata)." (PMID 25274085, 2014). "Previously we found that the BRCA1-AKT1 pathway contributes to tumorigenesis and that the AKT1/mTOR is a novel therapeutic target for BRCA1-deficient cancers." (PMID 24831086, 2014). "It has also been shown that the relative levels of BRCA1 isoforms associated with exon 11 alternative splicing differs between normal and cancer tissues." (PMID 25056543, 2014). "Pre-clinical reports and clinical trials have recently documented the increased sensitivity of cancers expressing BRCA1 mutation to PARP inhibitor, such as veliparib, and to DNA damaging agents." (PMID 25026298, 2014). "Until recently, it was believed that mutations in the BRCA1 C-terminal domain resulted in reduced HR, resulting in genomic instability and, ultimately, the development of cancer." (PMID 23599763, 2013). "The Consortium of Investigators of Modifiers of BRCA1/2 (CIMBA) is currently examining the role of various genetic modifiers of cancer risk in BRCA mutation carriers." (PMID 23517070, 2013). "Although PARP inhibitors displayed promising results for killing cancer cells with BRCA1/BRCA2 deficiency, there are several issues regarding PARP inhibitor-related therapies." (PMID 23388117, 2013). "Other transient features of the Xi during this time include the association of the breast cancer gene (BRCA1) and the phosphorylation of histone H2A.X at serine 139 (γ-H2A.X)." (PMID 24168170, 2013). "RAD51 135G>C can modify promoter activity and the penetrance of BRCA1/2 mutations, which plays vital roles in the etiology of various cancer." (PMID 24040396, 2013).
cancer (continued). "The aberrant hypermethylation of genes such as RB1, MLH1 and BRCA1, whose mutation is associated with inherited cancer predisposition, can be regarded as particularly significant." (PMID 23341493, 2013). "Increased sensitivity to DNA-damaging anti-cancer drugs has been associated with BRCA1 or BRCA2 functional loss involving germline mutations or epigenetic changes." (PMID 23964347, 2013). "In this group, only age was almost negatively associated with BRCA1 promoter methylation (83.3% of cancers were unmethylated in patients >54 vs. 58.3% in patients ≤54 years, p = 0.057)." (PMID 24191908, 2013). "The contenders were among the biggest names worldwide in human genetics research and, in the end, it was the team working with Mark Skolnick of Myriad Genetics that uncovered the BRCA1 sequence by finding cancer-associated mutations." (PMID 23369278, 2013). "Although it is not clear if all observed phenotypes contribute to BRCA1 mutations associated tumorigenesis, the function of BRCA1 in HR repair plays a critical role in BRCA1 associated cancer development." (PMID 23388117, 2013). "It has also stimulated an interest in chemoprevention for those deemed at increased genetic risk for developing cancer; for example, women carrying mutations in the BRCA1/2 genes are now being offered risk-reduction drugs such as tamoxifen." (PMID 23750174, 2013). "Our data indicate that loss of the BRCA1/p63/Notch signalling axis results in an increase in an aberrant population with cancer stem cell properties." (PMID 23863842, 2013). "Conversely, nPARP expression was significantly increased in cancers with BRCA1 or BRCA2 mutations compared to sporadic tumours." (PMID 24191908, 2013). "In humans, breast cancer-susceptibility 1 (BRCA1) and breast cancer-susceptibility 2 (BRCA2) genes have been found to be mutated in a large number of early-onset breast or ovarian cancers." (PMID 24004841, 2013). "In a mouse model with a knock-in cancer-associated Brca1 mutation-Cys61Gly), the tumors rapidly developed resistance to both olaparib and cis-platinum but retained the Brca1 mutation." (PMID 23802008, 2013). "PARP-1 inhibitors have been shown to be effective in selectively inducing synthetic lethality in cancer cells, particularly in BRCA1- or BRCA2-deficient tumours." (PMID 23405229, 2013). "A number of polymorphisms have been identified in the BRCA1 gene and P871L (rs799917) is one of the most common variants with a minor allele (T) frequency of 32% among Caucasian cancer patients." (PMID 23964347, 2013). "Genetic Modifiers of Cancer Risk in BRCA1/2 Mutation Carriers (GEMO): GEMO thanks all the GEMO collaborating groups for their contribution to this study." (PMID 23544013, 2013). "BRIP1 is a DNA helicase that directly interacts with the C-terminal BRCT repeat of the breast cancer susceptibility protein BRCA1 and plays an important role in BRCA1-dependent DNA repair and DNA damage–induced checkpoint control." (PMID 24040146, 2013). "The importance of the local tissue environment for a transformed cell to become a cancer is indicated by genetic cancer syndromes caused by highly penetrant mutations; such as Bloom syndrome, neurofibromatosis and BRCA1/2 mutations." (PMID 23907184, 2013). "Although both excision repair cross-complementing group 1 (ERCC1) and breast cancer susceptibility gene 1 (BRCA1) can be effective biomarkers for chemosensitivity in primary malignant tumors, their applicability to metastases is poorly understood." (PMID 23496813, 2013). "There are no specific treatment guidelines for TNBC patients, however, it has been postulated that their phenotypic and molecular similarity to BRCA1-associated cancers would confer sensitivity to certain cytotoxic agents, including platinum." (PMID 23426861, 2013). "The most important predisposing factors are germline mutations in inherited cancer susceptibility genes, most notably BRCA1, BRCA2, RAD51C, RAD51D and the mismatch repair genes." (PMID 23522120, 2013).
cancer (continued). "Several cancer-associated point mutations of the RING domain of BRCA1 (e.g., Cys61Gly and Cys64Gly) disrupted the BRCA1: BARD1 interaction, suggesting that this interaction contributes to BRCA1-dependent tumor suppression." (PMID 23802008, 2013). "The new test will initially cover twenty-five genes associated with different types of cancer, including eight currently-proprietary ones BRCA1, BRCA2 and MYH." (PMID 23885284, 2013). "It is important to know that BRCA1/2 associated cancers are quite rare and only account for less than 5% of breast-cancer patients so it is crucial to see how PARPis function on other cancers." (PMID 24289880, 2013). "The first-in-human clinical trial of the PARP inhibitor, olaparib, has been conducted in patients with BRCA1/2-mutated advanced cancers including ovarian, breast, and prostate cancers." (PMID 24063014, 2013). "Les mutations des gènes BRCA1 et BRCA2sont incriminées dans une proportion du cancer du sein chez l ́homme mais avec un moindre risque absolu que chez la femme et avec une fréquence plus faible." (PMID 24711870, 2013). "Olaparib (AZD2281), another PARP inhibitor, produced positive anti-tumor results in cancer patients with BRCA1/2 mutations." (PMID 24289880, 2013). "More specifically, a strong correlation between increased genomic instability, DNA repair defects, and cancer predisposition has been documented in cells isolated from individuals carrying germ line mutations in BRCA1 or BRCA2 genes." (PMID 23675572, 2013). "Inhibitors of PARP were originally developed for cancers with homologous recombination deficiencies, such as those harboring mutations in BRCA1 or BRCA2 genes." (PMID 24098868, 2013). "Ovaries from BRCA1 mutation carriers underwent prophylactic adnexectomy and control group of patients were operated from other than cancer reasons." (PMID 23553196, 2013). "A cancer familial history was present in 31.4% of the unrelated patients, from them 43.7% were carriers for germline mutation (37.5% in BRCA1 and in 6.2% in the BRCA2 genes)." (PMID 23469205, 2013). "It is therefore crucial to identify these individuals to offer appropriate cancer management and understand the contribution of BRCA1 and BRCA2 mutation-associated risks." (PMID 24137399, 2013). "Inhibitors of PARP were shown to be highly selective for cancer cells that harbor homologous recombination (HR) deficiencies, such as those harboring mutations in BRCA1 or BRCA2 genes." (PMID 24098868, 2013). "Uncovering other genes that become mutated subsequent to BRCA1/BRCA2 inactivation during cancer development will be helpful for more effective treatments." (PMID 23522120, 2013). "A single nucleotide polymorphism in the 5′-untranslated region (5′-UTR) of RAD51 (a G to C substitution at position 135, the G/C polymorphism) can influence cancer risk among BRCA1/BRCA2 mutation carriers." (PMID 24040396, 2013). "One study indicated that BLBC associated with BRCA1 gene inactivation expresses lower levels of p16 than carcinomas associated with inactivation of BRCA2, which were more frequently ER positive." (PMID 23717338, 2013). "BRCA1 is also believed to be a regulator in mammary stem cell differentiation and associated with cancer stem cells." (PMID 23077482, 2012). "Another study has shown that cancer causing mutations in other areas of the BRCA1 BRCT domain can alter the backbone structure of the BACH1 binding pocket." (PMID 22737296, 2012).
cancer (continued). "Here we studied fresh breast tissue from a BRCA1 mutation carrier who was initially treated with a lumpectomy and RT for a unilateral cancer and two years later chose a prophylactic bilateral mastectomy while remaining cancer-free." (PMID 23210696, 2012). "A total of 123 cases were cancer-free; it included 22 first-degree relatives of the index cases, 57 women with mutation (BRCA1/2), 34 relatives with mutation (BRCA1/2) and 10 relatives without mutation." (PMID 22187037, 2012). "Treatments with Poly(adenosine diphosphate ribose) polymerase (PARP) inhibitors have offered patients carrying cancers with mutated BRCA1 or BRCA2 genes a new and in many cases effective option for disease control." (PMID 24970153, 2012). "BRCA1 is rarely mutated in sporadic cancer cells, but epigenetic inactivation of BRCA1 has been documented." (PMID 26316936, 2012). "These included the generation of HuMMs harbouring codon-specific mutations for β-thalassemia and the BRCA1 cancer susceptibility gene." (PMID 22396661, 2012). "The inhibition of PARP alone is not sufficient to kill normal cells, but it results in an accumulation of lesions in the DNA and in repair-deficient BRCA1 or BRCA2 mutated cancers, these factors combined cause cell death." (PMID 24970153, 2012). "Recent work has indicated that HR defects exist in various cancer cells, with inherited mutations in HR-promoting factors such as BRCA1 and BRCA2 leading to elevated cancer predisposition." (PMID 22893507, 2012). "In patients diagnosed with cancer we found 4 novel deleterious mutations (c.2805_2808delAGAT and c.3124_3133delAGCAATATTA in BRCA1; c.2639_2640delTG and c.5114_5117delTAAA in BRCA2)." (PMID 22655046, 2012). "Cancer cells with defective DNA repair pathways, such as loss of BRCA1, inactivation of the BRCA1 DNA repair pathway, and synthetic lethality, alter their sensitivity to DNA-damaging agents or chemotherapeutic drugs." (PMID 23203101, 2012). "Structural studies of exons 11-13 as well as the rest of the BRCA1 protein will be necessary to elucidate the molecular basis by which mutations in these domains lead to cancer predisposition." (PMID 22737296, 2012). "BRCA-positive cases include cancer patients and their relatives carrying different BRCA1 or BRCA2 mutations." (PMID 22187037, 2012). "Cancers with BRCA1 or BRCA2 mutations exhibited a characteristic combination of substitution mutation signatures and a distinctive profile of deletions." (PMID 22608084, 2012). "Women with low FMR1 sub-genotypes, therefore, should reflect increased BRCA1/2-associated cancer risks, while the remaining approximately 75 percent should face almost no such risks." (PMID 22984553, 2012). "Preclinical studies have demonstrated that cancer cells with defective HR repair caused by either BRCA1 or BRCA2 inactivating mutations, display exquisite sensitivity to PARP inhibitors." (PMID 23251575, 2012). "Among the cases, 629 are cancer patients and 123 are cancer-free subjects, including 32 first-degree relatives of the susceptible subjects and 91 BRCA1/2 mutation carriers." (PMID 22187037, 2012). "Many cancer-predisposing mutations in the BRCA1 RING domain, that inhibited E3 ligase activity and its ability to accumulate at a damaged site, were defective in homologous recombination, which is critical for tumor suppression." (PMID 23203101, 2012). "Structural studies of the RING and BRCT domains have revealed the molecular basis by which cancer causing mutations impact the functions of BRCA1." (PMID 22737296, 2012). "BRCA1 mutated cancers are more sensitive to DNA damage inducing chemotherapy than their sporadic counterparts." (PMID 22032731, 2011). "BRCA1-associated cancers are typically triple-negative in phenotype, correlate with a poor clinical outcome, and are in need of improved treatment options." (PMID 21771338, 2011).